IL1A (interleukin 1 alpha)
Diseases named in the same sentence as IL1A in open-access papers (continued):
Sharing a sentence is not in itself a finding about the gene and the disease.
breast cancer (continued). "Others have begun to interrogate the genomic effects of 1,25(OH)2D3 in normal and malignant human mammary cells and in mouse mammary tumor cells, but we are the first to report IL1α as a target of 1,25(OH)2D3 signaling in mammary cells." (PMID 24244740, 2013). "IL1α activity has previously been reported in breast cancer cells outside of the context of vitamin D3." (PMID 24244740, 2013). "IL1A is thought to contribute to breast cancer expression by up-regulating pro-metastatic genes in breast cancer cells and stromal cells." (PMID 16842617, 2006). "The aim of this study was to evaluate any role of specific SNPs in the interleukin genes IL1A, IL1B, IL1RN, IL4R, IL6 and IL10 in predisposition to breast cancer susceptibility and severity." (PMID 16842617, 2006). "IL1A levels in breast tissue homogenates correlates inversely with ER levels, which is an established prognostic marker in breast cancer." (PMID 16842617, 2006). "This suggests that the IL-1A gene contributes to breast cancer in older women." (PMID 40584290, 2025). "We therefore designed IL-1α knockout 4T1 breast cancer cells using the CRISPR/Cas9 approach." (PMID 38612760, 2024). "Additionally, our results indicate that elimination of the microenvironment-derived IL-1α also inhibits the growth of breast cancer grafts in mice." (PMID 38612760, 2024). "Another niche study of fibroblasts in metastases found that IL-1α and IL-1β secreted by breast cancer cells induced CXCL9 and CXCL10 production in lung fibroblasts, which was also achieved through NF-κB signaling and ultimately promoted the progression of lung metastasis." (PMID 36759842, 2023). "The effector cytokines of inflammasomes can be different when it comes to spontaneous breast cancer mice models where genetic blockage of IL-1α/IL-1R1 signal develops higher tumor burden and increased mortality rate implying similar roles of IL-1α, IL-1β, and IL-18 in tumorigenesis." (PMID 36932407, 2023). "Previous studies have shown that IL-1α suppresses tumorigenesis in fibrosarcoma and breast cancer." (PMID 37998338, 2023). "The PyMT-B6 mouse breast cancer line expresses IL-1α and LIF in addition to G-CSF." (PMID 37134077, 2023). "Indeed, we find that vehicle-treated ErbB2-induced breast cancer tissue expresses Il1a, Il1b, Il6, and Nfkb1 at a measurable level." (PMID 37098526, 2023). "Moreover, a higher level of IL1α is positively correlated with more macrophage infiltration and shorter overall survival in breast cancer patients." (PMID 37551997, 2023). "Studies also showed TSLP enhances the lung metastasis of mammary tumour through an alveolar macrophage-dependent mechanism; and those induced by tumour-derived IL-1α in infiltrating myeloid cells can promote the survival of breast cancer cells and lung metastasis." (PMID 33652749, 2021). "Conversely, a study on mammary tumor cell proliferation in MMTV-PyMT breast cancer cell showed that IL-1α dependent IL-1R signaling could suppress tumor growth and curb pulmonary metastasis." (PMID 33430381, 2021). "However, an earlier study by another group showed that IL-1α was able to inhibit MCF-7 breast cancer cell growth at the G0/G1 phase of the cell cycle." (PMID 33430381, 2021). "Since IL-1α/β are secreted cytokines, we investigated whether CM of cultured breast cancer cells drives induction of CXCL9/10 in fibroblasts in vitro." (PMID 32198421, 2020). "Indeed, IL1A/B were expressed by MDA and SUM breast cancer cell lines, and IL1A/B expression levels were significantly increased in the respective lung metastatic derivatives, MDA-LM2 and SUM-LM1, suggesting an association with metastatic potential." (PMID 32198421, 2020). "For example, IL1β positively modulates TSLP production and secretion in DCs in vitro, and in a recent study, myeloid cells, including neutrophils and monocytes, have been shown to produce TSLP in response to IL1α, a mechanism that was responsible for breast cancer spreading." (PMID 32285594, 2020).
breast cancer (continued). "In addition, adipocyte-derived conditioned media induced phosphorylation of AKT and mTOR and upregulated the expression of target genes of the PI3K-AKT-mTOR pathway including IL6, IL1β, IL1α and TNFα in breast cancer cells." (PMID 32201525, 2020). "In line with the observed high IL1A/B mRNA and secreted protein levels by metastatic breast cancer cells, treatment with CM from MDA-LM2 or SUM-LM1 cancer cells induced a stronger upregulation of CXCL10 in MRC-5 fibroblasts compared to CM from parental cell counterparts." (PMID 32198421, 2020). "Finally, only one study evaluated IL-1α expression using an in vitro model where breast cancer cells were treated with an endothelin-1 (ET-1) receptor dual antagonist, showing a local increase in breast cancer cell secretions of IL-1α." (PMID 31847214, 2019). "A similar role for Il-1α was recently demonstrated in breast cancer." (PMID 31231372, 2019). "Finally, recent elegant work examining the relationship between HER2 expression in breast cancer, inflammation and expansion of cancer stem cells (CSCs) highlighted an essential role for IL-1α in this process." (PMID 31231372, 2019). "There is accumulating evidence indicating the presence of a peritumoural inflammatory infiltrate in BC, which may reflect, at least in part, an antitumour immune response.IL-1A and IL-1B expression was increased in human breast cancer tissues." (PMID 29719585, 2018). "The inhibition of IL-1R1 and reduced bone metastasis in our mouse model shows the role of this signalling axis in breast cancer metastasis to bone, but further studies are needed to elucidate whether IL-1B and/or IL-1A are primarily involved in this process." (PMID 29760166, 2018). "Importantly, the inhibitors reduced expression of the signature SASP factors IL-6 and IL-1α by cells made senescent by genotoxic stimuli, and suppressed the ability of senescent fibroblasts to stimulate breast cancer cell aggressiveness." (PMID 29402901, 2018). "In addition, Gene Set Enrichment Analysis (GSEA) of Zeb1 depleted breast cancer cells showed its activating role in the expression of inflammatory response genes IL-6, IL-8, and IL-1α." (PMID 30483264, 2018). "Recent in vitro data indicate that IL-1B and not IL-1A is the relevant cytokine linked to dormancy of breast cancer cells in this environment." (PMID 29760166, 2018). "IL-1α can induce matrix degradation and remodeling by breast cancer fibroblasts." (PMID 27169366, 2016). "Breast cancer cells can secrete IL-6 and IL-8 in response to IL-1α." (PMID 27169366, 2016). "The IL1A -889 polymorphism has been studied in two different cohorts and not shown to be associated with breast cancer." (PMID 16842617, 2006). "Therefore, we demonstrate that the IL1A expression level plays a pivotal role in the recurrence of breast cancer and could be a target for TNBC treatment." (PMID 34203721, 2021). "Hence, IL-R1 signalling could have both pro- and anti-tumour functions and it is possible that IL-1A and IL-1B may exert opposite functions in breast cancer progression." (PMID 29760166, 2018). "The aim of this study was to evaluate polymorphisms in specific cytokine genes [IL1A +4845G>T, IL1B -511C>T, IL1B +3954C>T, IL1RN +2018T>C, IL4R -1902A>G, IL6-174G>C and IL10-1082G>A] in a case control model to determine any associations with breast cancer susceptibility, severity and survival." (PMID 16842617, 2006). "However, to date, there are no published studies on the role of the IL1A +4845 polymorphism in breast cancer." (PMID 16842617, 2006). "The results from our study do not support the hypothesis that the cytokine polymorphisms studied [IL1A +4845G>T, IL1B -511C>T, IL1B +3954C>T, IL1RN +2018T>C, IL4R -1902A>G, IL6-174G>C and IL10-1082G>A] are associated with breast cancer susceptibility and severity." (PMID 16842617, 2006). "In this study, we have highlighted the significance of TGFβ-1, IL19, CXCR4, BMP1, IL1A, VCAN, PDK1, and WNT2 in breast cancer pathology." (PMID 41348904, 2025).
breast cancer (continued). "Surprisingly, the CXCL9/10-binding chemokine receptor CXCR3 was specifically expressed in a small subset of breast cancer cells, exhibited tumor-initiating capacity when co-transplanted with fibroblasts, and had high JNK signaling Drives IL-1α/β expression." (PMID 36759842, 2023). "Alternatively, long-term DEHP exposure can also induce upregulation of the inflammatory cytokines IL1α, IL1β, IL6, and GM-CSF through the MAPK/p38 signaling pathway to facilitate breast cancer progression." (PMID 35203627, 2022). "qPCR analysis of c-Jun-bound chromatin confirmed that c-Jun binds to IL1A and IL1B promoters in breast cancer cells." (PMID 32198421, 2020). "We selected a set of five inflammatory factors (IL1A, IL6, IL17A, IFNβ, and NFĸB) that were found to be overexpressed in aggressive breast carcinomas." (PMID 33396463, 2020). "As was observed with neutrophils from cancer-free controls, MCP-1, IL1RA, IL1A, and TNF were capable of significantly enhancing the cytotoxic activity of neutrophils from breast cancer patients." (PMID 28721376, 2016). "Later, IL1α was shown to inhibit estrogen-mediated growth and to decrease estrogen receptor levels in MCF-7 breast cancer cells, establishing an intersection between cytokine and hormonal signaling in mammary cells." (PMID 24244740, 2013). "Suppression of IL-1α expression in tumor cells and the TME, e.g., using nanoparticle delivery systems, could be a promising strategy for battling breast cancer." (PMID 38612760, 2024). "Despite the clinical signs, which resemble the presence of acute inflammation, IBCs produce inflammatory cytokines (such as IFNG, TNF, IL1A, IL1B, and IL8) at similar levels to other breast cancer subtypes, while the host inflammatory cell infiltration is low in the IBC stroma." (PMID 39103878, 2024). "We found that human breast cancer does not have the same cytokine profile as PyMT-B6 as it only overexpresses IL-1α but not LIF or G-CSF, while human colon cancer was the only cancer to overexpress all 3 cytokines." (PMID 37134077, 2023). "Doxorubicin at 100 nM can induce senescence in MDA-MB-231 breast cancer cells, and the SASPs of the senescent breast cancer cells include interleukin-6 (IL-6), IL-8, matrix metalloprotease-1 (MMP-1), IL-1α, and granulocyte-macrophage colony-stimulating factor (GM-CSF)." (PMID 36291773, 2022). "Moreover, ICAM3, CCL16, PDE3A, PRTN3, TRAF6, BCAR1, IL-1α, IL-1β, NFκB1, SOX2 and OCT4 decreases the protein expression as indicated by immunofluorescence staining in the ibuprofen-treated MDA-MB-231 breast cancer cells versus the control." (PMID 32528119, 2020). "However, IL1A, IL6, IL10, and NFĸB gene expression in CAF was increased, whereas MMP11 was decreased after co-culture with PBMC from breast cancer patients." (PMID 33396463, 2020). "Gene expression of MMP1 and MMP11 in PBMC from breast cancer patients (n = 54) and control (n = 28); expression of IL1A, IL6, IL17, IFNβ, and NFĸB in breast cancer cell lines (MCF-7 and MDA-MB-231); and, additionally, IL10 and MMP11 in CAF and NF were analyzed by qRT-PCR before and after co-culture." (PMID 33396463, 2020). "MCM and hCM greatly increased the expression of IL-6, IL-1β, IL-1α, TNF-α, IGF-1, and MCP-1 compared with control at the mRNA levels in MCF-7 and MDA-MB-231 cells, while the little effect on the VEGF expression in mCM treated-breast cancer cells." (PMID 32201525, 2020). "We tested whether IL1A, MCP-1, IL1RA, and TNF were capable of stimulating neutrophil cytotoxicity to determine whether the increased serum levels of these cytokines in breast cancer patients were directly related to the cytotoxic activity of neutrophils." (PMID 28721376, 2016). "Subsequent studies presented a correlation between IL1α expression, breast cancer severity, and ER-negativity, but no functional connections have been established." (PMID 24244740, 2013).
breast cancer (continued). "We found that the high level of IL-1β but not IL1-α was significantly correlated with a poor brain metastasis-free survival of breast cancer patients." (PMID 23495140, 2013). "Polymorphisms within key interleukin genes (IL1A, IL1B, IL1RN, IL4R, IL6 and IL10 do not appear to play a significant overall role in breast cancer susceptibility or severity." (PMID 16842617, 2006). "While IL-1α expression alone in MCF-7 breast cancer cells was not able to induce metastasis, a study on breast tumor-derived IL-1α resulted in metastatic spread by inducing the expression of thymic stromal lympopoietin (TSLP) from tumor-infiltrating myeloid cells." (PMID 33430381, 2021). "Notably, we find that the chemokine receptor CXCR3, that binds CXCL9/10, is specifically expressed in a small subset of breast cancer cells, which exhibits tumor-initiating ability when co-transplanted with fibroblasts and has high JNK signaling that drives IL-1α/β expression." (PMID 32198421, 2020). "Remarkably, we found that multiple genes that belong to the NLRP3 inflammasome pathway, including P2rx7, Nlrp3, Casp1, Il1a and Il1b are upregulated in CAFs isolated from mammary carcinoma, but not in normal mammary tissue, or in fibroblasts isolated from mammary hyperplasia." (PMID 31558756, 2019). "The results showed that higher expressions of IL1α and IL1β, but not IL8, are significantly correlated with shorter overall survival times for breast cancer patients." (PMID 37551997, 2023). "In 1988, recombinant IL1α was first reported to inhibit growth of estrogen-dependent breast cancer cell lines MDA-MB-415 and MCF-7, but not that of hormone-independent breast cancer cell lines (HS-578-T and MDA-231)." (PMID 24244740, 2013). "In contrast to nontreated con cells, for senescent human breast cancer MDA-MB-231 cells, the factors detected by arrays and secreted at a significant level are FGF-6, GM-CSF, IGFBP-1, MCP-1, IL-6, IL-1α, GRO a/b/g, GRO α, IL-8, MIP, MIP-1α, uPAR, ICAM-1, and MMP-1." (PMID 30871042, 2019).
Sepsis (80 papers, 2010 to 2026). Sepsis is defined as life-threatening organ dysfunction caused by a dysregulated host response to infection. "The mechanism through which granzyme B is associated with sepsis is as follows: Granzyme B influences cytokine activation by cleaving IL-1α precursors, enhancing its pro-inflammatory effects." (PMID 40094854, 2025). "In particular, the presence of the homozygous IL-1A rs1800587TT genotype appears to be a significant risk factor for sepsis, septic shock and neurological symptoms." (PMID 36551320, 2022). "We found sepsis-associated DVPs in genes important for immune response against infection and hyperinflammation such as IL1A and TNF." (PMID 31665078, 2019). "We also identified thrombin-cleaved IL-1α in humans with sepsis-associated adult respiratory distress syndrome (ARDS)." (PMID 30926232, 2019). "In this study, two polymorphisms (IL-1β (−511) and IL-1R) were significantly associated with the development of MOF and mortality, where as IL-1α (−889) polymorphism associated with susceptibility for sepsis." (PMID 26561011, 2015). "The IL-1 gene polymorphism corresponding to IL-1α (−899), IL-β (−511) and IL-1β (+3962) were analyzed between patients with sepsis and non-sepsis." (PMID 26561011, 2015). "In this study, two polymorphisms (IL-1β (−511) and IL-1R) were significantly associated with the development of MOF and mortality where as IL-1α (−889) polymorphism was associated with susceptibility for sepsis." (PMID 26561011, 2015). "Only two studies with high quality containing 193 cases and 193 controls evaluated the association of the IL-1A-889 polymorphism (rs1800587) with sepsis risk." (PMID 24428862, 2014). "However, due to limited research on the relationship between IL-1α genetic polymorphism and sepsis, it was excluded from consideration." (PMID 38848433, 2024). "For example, although we showed p18 IL-1α is generated during sepsis-associated ARDS, it would be valuable to determine whether p18 affects or correlates (e.g. as a biomarker) to clinical outcome." (PMID 30926232, 2019). "Other studies have demonstrated that IL-1α plays a role in neonatal susceptibility to sepsis." (PMID 31354715, 2019). "In this meta-analysis, two polymorphisms (IL-1B + 3594 and IL-1RN VNTR) were significantly associated with sepsis susceptibility in overall comparison and subgroup analyses based on sepsis severity, whereas IL-1A-889 polymorphism influenced sepsis risk only in overall comparison." (PMID 24428862, 2014). "Importantly, we also identified p18 IL-1α in humans with sepsis-associated ARDS." (PMID 30926232, 2019). "IL1A, also known as hematopoietin 1, promotes fever and sepsis during inflammation, and has numerous important functions in the inflammation process, including the stimulation of lymphocyte production." (PMID 40995220, 2025). "Most IL-1 sepsis research and clinical investigation has focused on IL-1β, with IL-1α receiving less attention." (PMID 37928695, 2023). "In accordance, IL-1α has been used as a predictor biomarker for several chronic and autoimmune diseases such as sepsis, diabetes, and nephropathy." (PMID 37457235, 2023). "IL-6 and IL-1α are important mediators of the acute-phase response and are released in the event of sepsis, ischemic injury, or toxicity." (PMID 36993800, 2023). "IL-1α is present in thrombo-inflammatory conditions like sepsis, where it is released by epithelial cells and has the role of an alarmin; it activates the inflammatory cascade." (PMID 36295093, 2022). "Specifically, evoked supernatant concentrations of TNF, IL-6, IL-1α, IL-1β, and IL-8 were all substantially less in assays of sepsis patients’ samples, despite greater baseline concentrations and ongoing inflammatory activity when compared to controls." (PMID 35981050, 2022).